BRAF (B-Raf proto-oncogene, serine/threonine kinase)
Diseases named in the same sentence as BRAF in open-access papers (continued):
Sharing a sentence is not in itself a finding about the gene and the disease.
melanoma (continued). "The study based on melanoma cell line and melanocytes proved that BRAF V600E mutation-induced transcription of IL1B." (PMID 35163468, 2022). "Second line anti-PD1 immunotherapy is effective in BRAF-mutated melanoma patients after BRAFi/MEKi therapy failure." (PMID 35565255, 2022). "In this real-world, retrospective analysis, we present the outcomes of 135 patients with stage IV BRAF-mutated melanoma who received consecutive treatment with BRAF/MEKi and CPI, or vice versa." (PMID 35565212, 2022). "We conclude that NQO1 is located downstream of UBIAD1 and cooperates with it to protect BRAF-mutated melanoma cells from lipid peroxidation and cell death." (PMID 35255427, 2022). "Approximately 50% of melanoma carries activating mutations in the BRAF oncogene, leading to the activation of the mitogen‐activated protein kinase (MAPK)/ERK pathway." (PMID 34957688, 2022). "Among the more than 20 different BRAF mutations in melanoma, the BRAFV600E mutation is the most prevalent and accounts for 90% of all BRAF mutations in melanomas." (PMID 35883549, 2022). "In BRAF V600E-mutated malignant melanoma, a frequent mechanism of acquired resistance to BRAF inhibitors involves alternative splicing (AS) of BRAF." (PMID 35883549, 2022). "BRAF‐mutated melanoma cells (1205Lu) were subcutaneously xenografted into nude mice (CDX model), which were exposed to BRAFi, imatinib, or BRAFi plus imatinib." (PMID 34957688, 2022). "In ultraviolet-shielded melanoma, mutations of BRAF, NRAS or NF1 are less frequent compared to cutaneous melanoma, but the existence of other cancer driver gene mutations are detected." (PMID 35688842, 2022). "The discovery of the presence of BRAF gene mutations in melanoma cells has led to extensive research and development of selective BRAF inhibitors." (PMID 35159044, 2022). "Durvalumab, an anti-PDL1, has also been used in combination with dabrafenib and trametinib in patients with both BRAF-mutated and BRAF-wild-type advanced melanoma in a phase I clinical trial (NCT02027961)." (PMID 36358912, 2022). "Among these, the sequence of targeted and immune checkpoint therapy showed promising results in terms of safety and efficacy in patients with metastatic or unresectable melanoma with a BRAF mutation." (PMID 35742834, 2022). "A multicenter, randomized (3:1) study, which enrolled 250 patients with previously untreated metastatic or BRAF V600E-mutated unresectable melanoma, evaluated the efficacy of dabrafenib 150 mg twice a day compared to dacarbazine in BREAK-3 study." (PMID 35742834, 2022). "We observed a significant expression of UBIAD1 protein in most of the melanoma cells tested, with BRAF-mutated cell lines (except for RPMI-7951) showing the highest amount of UBIAD1." (PMID 35255427, 2022). "These drugs are administered for melanomas and lung cancers harboring BRAF V600E mutations, and the combination showed meaningful responses in 33% of high-grade and 69% of low-grade gliomas in a Phase II clinical trial." (PMID 36147920, 2022). "In the IMspire150 phase 3 randomized trial, addition of atezolizumab to BRAF/MEK targeted therapy in patients with BRAF(V600)-mutation advanced melanoma was tolerable and significantly increased PFS." (PMID 35493449, 2022). "Immunosuppression, chronic wounds, and BRAF inhibitors for the treatment of melanoma are among additional risk factors for cSCC." (PMID 35646967, 2022). "According to the drug selection study, 75 mg b.d turned out to be almost as beneficial as 150 mg b.d. dabrafenib in treating BRAF-mutated melanoma." (PMID 35214043, 2022). "It has already been validated for testing for specific mutations that are characteristic of a variety of tumors, such as BRAF mutations in melanoma or EGFR in non-small cell lung cancer." (PMID 35159044, 2022).
melanoma (continued). "The experience and knowledge accumulated over the last few years have elucidated that BRAF-mutated melanoma is a more aggressive tumor than BRAF wild-type melanoma, with greater growth rate and a greater capacity for metastasizing." (PMID 36143339, 2022). "BRAF is one of the most commonly mutated genes in melanoma, the percentage of mutations ranging from 40 to 60%." (PMID 35326682, 2022). "A prominent example of genetic alterations in cell growth regulatory genes that has been associated with specific colon cancers and melanomas is a single point mutation in the BRAF gene." (PMID 36012578, 2022). "A great breakthrough was the approval of the B-Raf Serine/Threonine Kinase (BRAF) inhibitor named Vemurafenib in treating BRAF-mutated melanoma in 2002." (PMID 35372044, 2022). "There are a handful of early genetic events linked to the development of melanoma in situ, including mutations in BRAF, NRAS, or NF1." (PMID 36143375, 2022). "Dabrafenib plus trametinib is now applied as one of the first-line therapies for advanced NSCLC or melanoma with a BRAF(V600E) mutation." (PMID 36145516, 2022). "Currently, single or combined therapies of MAPK inhibitors Trametinib, Abrafenib, and Vemurafenib have been used in BRAF V600-mutated melanoma 56-58, BRAF-mutated non-small cell lung cancer 59,60 and anaplastic thyroid cancer." (PMID 35982904, 2022). "CCT196969 seems to be an effective inhibitor of cell viability in EGFR-mutated melanoma, as well as in BRAF inhibitor resistant melanoma which has achieved resistance with upregulation of the STAT3 pathway." (PMID 36084109, 2022). "BRAF mutations represent a diagnostic criterion for melanoma, but recently it was associated with AD." (PMID 36362022, 2022). "In 60% of melanoma cases, the primary cause is BRAF mutation, thus we analyzed the effect of NPC-402 on BRAF expression and observed that BRAF is significantly downregulated by 3-fold at higher concentrations." (PMID 35982963, 2022). "A systematic resequencing investigation involving 545 cancer cell lines revealed that oncogenic BRAF mutations are highly recurrent in melanoma." (PMID 36551688, 2022). "BRAF is an oncogenic serine/threonine kinase, which is mutated in various cancers, most commonly in melanoma, thyroid carcinomas, hairy cell leukemia, lung cancers, and colorectal cancers." (PMID 36295658, 2022). "Overall, the present study enabled the selection of n-BuOH as the G18.EE fraction with the highest activity against the most aggressive melanoma type (BRAF-mutated melanoma)." (PMID 35684471, 2022). "Non-V600 BRAF-mutated melanoma remains a therapeutic challenge if treatment with checkpoint inhibitors fails." (PMID 35380338, 2022). "One example of deregulation is BRAF, a proto-oncogene mutant that encodes serine/threonine protein kinase B-Raf and is found in 40%–50% of melanoma cases." (PMID 36699049, 2022). "BRAF V600 mutated melanomas have shown specific dermoscopic features compared to wild type (WT) melanomas." (PMID 35160279, 2022). "Rho pathway regulating actin-based motility is well known as an important regulator of cancer invasion and metastasis and has also been linked to BRAF inhibitor resistance in melanoma." (PMID 35883549, 2022). "The ability to detect somatic TERT promoter mutations co-occurring with BRAF or NRAS mutations is also valuable given that a TERT-mutation positive genetic profile is associated with a worse prognosis for melanoma patients." (PMID 35494035, 2022). "The discovery of the BRAF V600E hotspot mutation led to development of targeted molecular therapies for melanoma." (PMID 36613518, 2022).
melanoma (continued). "In about 80% of melanomas, the main oncogenic drivers involve mutations in B-Raf proto-oncogene serine/threonine kinase (BRAF) and neuroblastoma rat sarcoma viral oncogene homolog (NRAS)." (PMID 35490363, 2022). "Together, these results suggest that CDK12 is hyperactivated in BRAF-mutated melanoma and that its inhibition reveals prominent synthetic lethal targets." (PMID 36309522, 2022). "Together these data suggest that common abnormalities of melanomas linked to tumorigenesis – amplified centrosomes and whole-genome doubling events – can be induced by oncogenic BRAF and other mutations that increase RAS/MAPK pathway activity." (PMID 35840569, 2022). "Epidemiologically, BRAF mutated V600K melanomas seem to be more common in older and male patients, often with a history of CSD." (PMID 35160279, 2022). "Clinical efficacy of MAPK inhibition for non-V600 BRAF-mutated melanoma is generally lower than for V600 mutations [13••]." (PMID 35380338, 2022). "As SK-MEL-28 and A11 represent a BRAF-mutated and a BRAF-wildtype melanoma cell line and achieved a similar histopathology compared to melanoma in vivo, further model construction focused on these two cell lines." (PMID 36175453, 2022). "Overactivation of the RAS-RAF-MEK pathway is observed in about 90% of melanomas and the predominant mutation affects the BRAF gene in 50–70% of cases." (PMID 36286442, 2022). "The BRAF V600E mutation is well known for its role in melanoma, and BRAF inhibitors such as dabrafenib have already been shown to be fairly effective in advanced CRCs with the BRAF V600E mutation in clinical studies." (PMID 34042312, 2022). "In this study we demonstrate that wide changes in alternative splicing in melanoma cells occur in the presence of the mutated oncogene BRAF V600E and vemurafenib." (PMID 35883549, 2022). "Overall, these studies have indicated that BRAF mutations play an important role in melanoma development, maintenance, and progression." (PMID 35974375, 2022). "Deregulated activation of the BRAF V600E-dependent MAPK/ERK effectors is best recognized in the mechanisms underlying melanoma genesis and the growth of papillary thyroid cancer." (PMID 35163468, 2022). "This selective BRAF inhibitor successfully reduced tumor growth in the models harboring BRAF-mutated melanoma cells." (PMID 36175453, 2022). "Specifically, BRAF inhibition has led to low FDG uptake in BRAF-mutated melanomas in xenografts as well as in patients." (PMID 35327519, 2022). "We found increased activity of the cytoskeletal-associated MARCKS protein in BRAF inhibitor-resistant melanoma cells compared to BRAF inhibitor-sensitive melanoma cells and explored the mechanism behind this increased activity." (PMID 36551563, 2022). "Putative oncogenic activating mutations in BRAF (with a frequency of 40–60% in melanomas), NRAS, and KIT, as well as gene fusions, can signal through the MAPK and PI3K pathways, leading to uncontrolled cellular growth, proliferation, and survival." (PMID 34831002, 2021). "In silico analysis of tumors from MITF-E318K melanoma carriers in the TCGA Pan-Cancer-Atlas dataset confirmed the association with BRAF mutation and 9p21.3 deletion revealing a common genetic pattern." (PMID 34573422, 2021). "Up to 95% of BRAF-mutant melanomas have the V600E mutation, which confers an approximately 12% increased risk of brain metastases compared to wildtype patients." (PMID 34679325, 2021). "The objective of this appraisal was to compare the clinical and cost-effectiveness of Enco + Bini versus Dab + Tram for adults with advanced (unresectable or metastatic) BRAF V600 mutation-positive melanoma." (PMID 32291725, 2021). "It is well known that the MAPK signaling pathway is activated in up to 80–90% of melanoma patients, through 20–80% of BRAF mutation or 25% of NRAS mutation." (PMID 33917428, 2021).
melanoma (continued). "BRAF mutations have been identified in melanomas as a result of intermittent sun exposure, whereas melanomas arising from skin that was unexposed to the sun rarely showed BRAF mutations." (PMID 34680938, 2021). "After treatment of BRAF mutated melanoma cells with BRAFi or MEKi, we observed a reduction of EZH2 protein as well as mRNA for melanoma." (PMID 34063443, 2021). "PTEN silencing in BRAF-mutant melanoma cell lines has been associated to a decreased ability of T-cells to kill the tumors." (PMID 34123788, 2021). "The RAC1 P29S mutation works along with BRAF to promote melanoma initiation and cause resistance to BRAF inhibitors." (PMID 34804979, 2021). "We found four BRAF-mutant MCPyV-associated melanoma cases in our study subjects, which was discordant with earlier findings, where no virus-positive melanoma cases were found and, thus, the mutation status was not analyzed." (PMID 33535453, 2021). "Ott and co-workers demonstrated that cytokine generation and expression of activation markers in DC cocultured with BRAF-mutated melanoma cells were strongly impaired, while MAPK inhibition reversed this effect." (PMID 34576054, 2021). "A previous study in patients with BRAF V600-mutated non-melanoma cancer showed that monotherapy with the BRAF inhibitor vemurafenib had limited efficacy in CRC patients." (PMID 33446148, 2021). "Highly recurrent mutations in the BRAF V600 codon, which accounts for 35-50% of melanoma, and the Q61 codon, which accounts for 10-25% of melanoma, contribute to the evolution of highly selective kinase inhibitors for the MAPK pathway." (PMID 34804979, 2021). "Although each of these drugs demonstrated little or no activity as single agents, the three-drug combination showed significant activity against the BRAF-mutant melanoma cells harboring PTEN-mutation." (PMID 34331013, 2021). "Although the main events leading to melanoma progression and drug resistance are genetic events (mainly BRAF and NRAS mutations), epigenetic mechanisms are also important." (PMID 34063141, 2021). "The most common mutation in the BRAF gene found in melanoma patients is the substitution of a glutamic acid for a valine at the amino acid 600 position (V600E)." (PMID 34537078, 2021). "To date, two largely mutually exclusive groups of cutaneous melanomas can be categorised: those harbouring an activating BRAF mutation (mostly BRAF V600E), which represent 40–50% of all melanoma patients, and those harbouring other mutations than BRAF." (PMID 33801689, 2021). "The involvement of histone modifications in CM development has been suggested since benign nevi, which usually carry the BRAF V600E oncogenic mutation, rarely become melanoma, as this conversion requires additional events." (PMID 34575678, 2021). "The Telomerase Reverse Transcriptase (hTERT) promoter mutations, which were first identified in melanomas, often in combination with BRAF mutations, were reported to activate the telomerase and to be implicated in tumorigenesis." (PMID 34105069, 2021). "The highest frequency of BRAF mutations is detected in malignant melanoma, which constitutes a therapeutic target for patients with advanced melanoma." (PMID 33498201, 2021). "About half of all melanomas carry a specific mutation in the BRAF and MEK genes known as V600E and V600K, respectively." (PMID 33546290, 2021). "Epithelial-mesenchymal transition (EMT) and the stemness potency in association with BRAF mutation arein dispensable to the progression of melanoma." (PMID 34308569, 2021). "Future studies should explore the framework of these paradox inhibitors to design a therapeutic that overcomes resistance caused by BRAF amplification in melanoma." (PMID 33807778, 2021). "Overall, traditional 2D platforms provide a valuable contribution to in vitro cell biology study and have led to several landmark discoveries, including the predominance of BRAF V600E mutations in melanoma." (PMID 34831311, 2021).
melanoma (continued). "A microfluidic chip with a concentration gradient of vemurafenib was utilized to rapidly obtain therapy-resistant clones from two melanoma cell lines with the BRAF V600E mutation (A375 and SK-MEL-28)." (PMID 33840166, 2021). "The first generation of BRAF inhibitors (dabrafenib, vemurafenib), targeting BRAF V600E mutation, were taken over from melanoma treatment." (PMID 34572171, 2021). "In our previous study, we reported GNF-7 and its derivative SIJ1227 capable of strongly inhibiting melanoma cells with class I (A375)/class II (C8161) BRAF mutations and lung cancer cells with class II (H1755)/class III (H1666) BRAF mutations." (PMID 33917428, 2021). "Meta-analysis has demonstrated that BRAF mutation is an absolute risk factor for survival in melanoma patients." (PMID 34035810, 2021). "The identification of the BRAFV600E/K as an oncogenic driver of somatic mutation in melanomas resulted in the development of the targeted treatment of the BRAF gain-of-function mutation (GOF)." (PMID 34831002, 2021). "While mono- and combination therapies to target the MAPK cascade did induce a therapeutic response in BRAF-mutated melanomas, the development of resistance to MAPK-targeted therapies remains a challenge for a high proportion of patients." (PMID 34066022, 2021). "Having demonstrated that miR-129-5p expression is mediated by constitutive active BRAF/MEK signaling in BRAF mutated melanoma, we investigated its expression during long term BRAFi or MEKi treatment." (PMID 34063443, 2021). "BRAF mutation occurs in more than 80% of melanoma patients, with the V600E mutation being the most frequently observed." (PMID 33840166, 2021). "Recent studies have shown that different dermoscopic features are associated with important prognostic parameters of melanoma, such as BRAF mutational status and sentinel lymph node status." (PMID 33954019, 2021). "For BRAF mutation in the context of melanoma, reflex testing criteria should include advanced disease characteristics, as these patients would benefit the most from rapid initiation of BRAF/MEK inhibitors." (PMID 34068774, 2021). "Recently, a study reported that 3D melanoma cells (mutated BRAF and mutated NRAS melanoma cells) were significantly more sensitive than 2D cells to a combined treatment (dabrafenib and trametinib)." (PMID 34638245, 2021). "BRAF is a treatment target in melanoma patients, as studies have found it to be mutated in over 60% of cutaneous melanomas." (PMID 33807778, 2021). "The BRAF V600E mutation is a common mutation that occurs in many types of cancers, such as colorectal cancer, papillary thyroid cancer and melanoma." (PMID 33557011, 2021). "Specifically, V600E|V600M BRAF mutated melanomas downregulated let-7b-3p|0|−1(+1U), miR-100-5p|0|0(+1U), miR-125b-5p|0|0, miR-221-3p|0|−1, and upregulated let-7a-5p|+1|−2, miR-1247-5p|0|−1, miR-219a-1-3p|0|0 compared to V600E BRAF mutated melanomas." (PMID 34698264, 2021). "It is well known that BRAF mutations occur in more than 50% of CM, and targeted therapy for melanoma has been applied clinically which achieved good efficacy." (PMID 34044811, 2021). "Metastatic melanoma (MM) is a highly mutated type of cancer and can be classified into four groups depending on the driver mutation observed—mutation in BRAF (~50% of melanomas), NRAS (~30%), NF1 (10–15%) or triple wildtype." (PMID 34066022, 2021). "For example, the treatment of melanoma cells with the combination of BRAF inhibitor and MEK inhibitor showed either a loss of NF1 expression or an acquired mutation." (PMID 34362135, 2021). "We retrospectively analyzed 683 patients with BRAF‐mutated advanced melanoma treated with first line (1L) immunotherapy (N = 266) or targeted therapy (N = 417)." (PMID 34137219, 2021).